APOB (apolipoprotein B)
Diseases named in the same sentence as APOB in open-access papers (continued):
Sharing a sentence is not in itself a finding about the gene and the disease.
hepatitis B (5 papers, 2014 to 2025). "In patients with hepatitis B, PAF-AH activity correlated with total bilirubin (r = 0.633), total bile acid (r = 0.559), aspartate aminotransferase (r = 0.332), apolipoprotein B (r = 0.348), high-density lipoprotein cholesterol (r = −0.493), and apolipoprotein AI (r = −0.530)." (PMID 24973921, 2014). "Six IA genes, APOB, IMPDH1, SEC61G, IQGAP2, TAGAP, and IGKV4-1, were dysregulated (differential expression, p < 0.05) in only tumor samples of drinkers without hepatitis B virus (HBV) infection as compared to pure normal samples (from nondrinkers)." (PMID 31480259, 2019). "We found that the activity of circulating PAF-AH in patients diagnosed with hepatitis B was positively correlated with TBIL, TBA, ALT, AST, TG, and apoB, negatively correlated with ChE, HDL-c, and apoAI, and not correlated with Glu, BMI, Tch, and LDL-c." (PMID 24973921, 2014).
hyperlipoproteinemia (5 papers, 2006 to 2024). An elevated concentration of lipoproteins. "Type III hyperlipoproteinemia is an uncommon disorder, which cannot be diagnosed based on a conventional lipid panel but can be accurately recognized based on total cholesterol, triglyceride and apoB." (PMID 33598387, 2021). "There are, nevertheless, two exceptions to the rule that apoB captures the full atherogenic potential of the apoB lipoproteins: Lp(a) and the abnormally cholesterol-rich remnant particles in type III hyperlipoproteinemia." (PMID 33598387, 2021).
Impaired glucose tolerance (5 papers, 2011 to 2022). An abnormal resistance to glucose, i.e., a reduction in the ability to maintain glucose levels in the blood stream within normal limits following oral or intravenous administration of glucose. "In particular, the intake of alcohol was found to be inversely associated with apoB/apoA-I in a study sub-sample of post-menopausal 64-years old women, two thirds of whom were diabetic or had impaired glucose tolerance." (PMID 22848405, 2012). "Second, we did not evaluate certain other conventional lipid parameters, such as apolipoprotein B. Finally, some participants in our study had impaired glucose tolerance, which cannot be estimated by FBG, and impaired glucose tolerance may affect vessel function." (PMID 35931987, 2022).
liver fibrosis (5 papers, 2019 to 2026). "The current study also demonstrated that T-Chol, LDL-C, and ApoB levels were associated with both short-term and long-term improvements in liver fibrosis." (PMID 38808546, 2024). "apoB levels increased from baseline to 24 weeks after treatment in patients treated with RBV irrespective of the degree of liver fibrosis." (PMID 30884773, 2019).
renal dysfunction (5 papers, 2020 to 2022). "Finally, this study lacked data on apolipoprotein A, apolipoprotein B, remnant-like particle cholesterol and other atherogenic lipid indexes, which could provide more evidence on the link between lipid parameters and renal dysfunction." (PMID 33588849, 2021). "We found a linear relationship between early renal dysfunction and LDL-C, Apolipoprotein B, and Apolipoprotein B/A1 ratio, which was in all cases negative and small (r = −0.27, −0.23 and −0.16, respectively)." (PMID 34066182, 2021).
thyroid cancer (5 papers, 2023 to 2024). "Lipid-lowering APOB variants were associated with a decreased risk of thyroid cancer (OR 0.52; 95% CI: 0.36 to 0.75; p-IVW=4.29×10-4, FDR=2.81×10-3)." (PMID 38127052, 2023). "Lipid-lowering APOB variants were associated with a decreased risk of thyroid cancer (q<0.05)." (PMID 38127052, 2023). "Observing the identified OR values, HDL cholesterol might be the risk factor (OR > 1, p < 0.05) and “total cholesterol”, “apolipoprotein B”, and “ratio of apolipoprotein B to apolipoprotein A1” were the protective factors (OR < 1, p < 0.05) for thyroid cancer." (PMID 38189054, 2023). "This suggests that the role of lipids in aggressive thyroid cancer progression is mediated through APOB." (PMID 38067270, 2023). "Meanwhile, the slope of the line for “total cholesterol”, “apolipoprotein B”, and “ratio of apolipoprotein B to apolipoprotein A1”, respectively, was negative, suggesting that an increase of those apolipoprotein led to a reduced risk of thyroid cancer." (PMID 38189054, 2023). "Finally, given the relatively small number of studies on LDL-C/HDL-C ratio, ApoA-I, ApoB, and ApoB/ApoA-I ratio, more research is needed to validate the null findings of the present study on these biomarkers in thyroid cancer." (PMID 36672472, 2023).
vitamin D deficiency (5 papers, 2013 to 2025). A nutritional condition produced by a deficiency of VITAMIN D in the diet, insufficient production of vitamin D in the skin, inadequate absorption of vitamin D from the diet, or abnormal conversion of vitamin D to its bioactive metabolites. "The results of the present study also imply the role of vitamin D deficiency and the ApoB/ApoA-I ratio in the progression of DR." (PMID 38786290, 2024). "Alterations in the NLR, PLR, MLR, and SII seem to provide prognostic information regarding the response to bevacizumab in patients with DME, whilst vitamin D deficiency and the ApoB/ApoA-I ratio could contribute to better staging." (PMID 38786290, 2024). "This study examines the correlation between serum vitamin D levels with Apolipoprotein B (Apo B), and the Framingham Risk Score (FRS) and evaluates the impact of correcting severe vitamin D deficiency on Apo B levels and FRS among a group of Iraqi population." (PMID 40610878, 2025). "After adjusted for age, sex, BMI, PAL, smoking and alcohol consumption, subjects with vitamin D deficiency indicated significant differences in metabolic variables compared with vitamin D sufficiency group except for insulin, TC, LDL-C and apoB." (PMID 23320821, 2013).
acute pancreatitis (4 papers, 2019 to 2025). An acute inflammatory process that leads to necrosis of the pancreatic parenchyma. "This study investigated the association between serum ApoB/A1 ratio at admission and acute pancreatitis (AP) severity." (PMID 31123322, 2019).
aortic valve stenosis (4 papers, 2019 to 2025). Aortic valve stenosis (AVS) is a condition characterized by narrowing of the heart's aortic valve opening. "Apolipoprotein B/apolipoprotein A‐I (apoB/apoA‐I) ratio and lipoprotein(a) (Lp[a]) are associated with aortic valve stenosis (AVS) disease progression." (PMID 31407609, 2019). "However, risk analysis of rapid progression of aortic valve stenosis showed a trend for higher IgG against to ApoB-IC levels and the lowest tertile of IgM against to MDA-LDL." (PMID 36975592, 2023). "Oxidized phospholipid apoB and elevated lipoprotein (a) are predictive of faster disease progression in patients with established aortic valvular stenosis." (PMID 40870420, 2025).
cerebral infarction (4 papers, 2020 to 2024). An ischemic condition of the brain, producing a persistent focal neurological deficit in the area of distribution of the cerebral arteries. "Other studies further confirm our conclusions that this polymorphism of the APOB XbaI gene might increase the risk of cerebral infarction, and that the T allele is such a risk factor." (PMID 33836655, 2021). "Targeted lowering of both LDL-C levels and ApoB/ApoA-I may provide additional benefits for patients with cerebral infarction." (PMID 38274879, 2023).
cholangiocarcinoma (4 papers, 2021 to 2024). A carcinoma that arises from the intrahepatic biliary tree (intrahepatic cholangiocarcinoma) or from the junction, or adjacent to the junction, of the right and left hepatic ducts (hilar cholangiocarcinoma). "Meanwhile, APOB also might be associated with the immune cell infiltration in cholangiocarcinoma." (PMID 34997982, 2022). "Reviewing the literatures, we found that APOB played a role as an oncogene in many tumors, but not as a potential tumor suppressor gene in cholangiocarcinoma as we found." (PMID 33954113, 2021).
endotoxemia (4 papers, 2012 to 2023). "A small but statistically significant association with endotoxemia was observed for apoA1, whereas the associations for apoB and apoB/apoA1-ratio were considerably stronger." (PMID 33243051, 2021). "New evidence shows that a high-fat diet results in increased plasma triacylglycerol and apolipoprotein B levels, and can significantly decrease endotoxemia and bacterial translocation after hemorrhage." (PMID 23226457, 2012). "Studies have found a rapid and significant decrease in serum cholesterol, phospholipids, apoB, and apoA-I carried in LDL and HDL during acute phase reactions to endotoxemia and various inflammatory in humans." (PMID 38274232, 2023).
hepatic (4 papers, 2017 to 2024). "Additionally, hepatic IR is associated with overexpression of protein-tyrosine phosphatase 1B, which in turn contribute to the increased synthesis and secretion of apoB." (PMID 32546165, 2020). "This study first aimed to verifying that the ApoB/ApoA1 ratio is strongly correlated with CHB disease progression, and its predictive potential is not correlated with potential risk factors (e.g., age, anti-hepatitis treatment, and duration of chronic hepatitis)." (PMID 38744926, 2024).
HIV-1 infection (4 papers, 2012 to 2023). The type species of lentivirus and the etiologic agent of acquired immunodeficiency syndrome (AIDS). "APOBEC3G (A3G) belongs to the apolipoprotein B mRNA editing enzyme catalytic polypeptide-like (APOBEC) family of proteins and was initially identified as a potent restriction factor against HIV-1 infection in human CD4+ T cells." (PMID 25762005, 2015). "In contrast, ApoB, a primary apolipoprotein of chylomicrons, VLDL, IDL, and LDL, was not induced by HIV-1 infection, since ApoB is expressed primarily in liver and small intestine, but not in other tissues." (PMID 30496280, 2018).
hypertrophic cardiomyopathy (4 papers, 2021 to 2025). A condition in which the myocardium is hypertrophied without an obvious cause. "The GRS for lower FEV1/FVC specific to the hypertrophic cardiomyopathy pathway was associated with reduced liver enzymes (ALT and GGT) as well as lower apolipoprotein B, LDL, IGF-1 and mean platelet volume." (PMID 36914875, 2023).
macrosomia (4 papers, 2016 to 2025). "Mediation analysis showed that ApoB and the TG/HDL-C ratio mediated the harmful effects of FBG on the risk of macrosomia." (PMID 36035400, 2022). "Lower APOB methylation levels in specific CpGs located on islands were detected in the macrosomia group by 450K." (PMID 27888796, 2016). "The average methylation level of APOB in chr2: 21266623–21267021 in the macrosomia group was lower than that in the control group (P = 0.02)." (PMID 27888796, 2016). "Moreover, a matched cohort study found that a serum ApoB level > 4.04 g/L combined with a TG/HDL-C ratio > 1.36 could predict the occurrence of macrosomia in the GDM and normal glucose tolerance (NGT) groups." (PMID 36035400, 2022). "Pre-pregnancy BMI, total cholesterol, apolipoprotein B, and low-density lipoprotein levels were also higher in the GDM with macrosomia group, but without statistical significance." (PMID 40797060, 2025).
malaria (4 papers, 2010 to 2018). Malaria is a serious and sometimes fatal disease caused by a parasite that commonly infects a certain type of mosquito which feeds on humans. "The APOB plasma protein has been previously reported to have an altered expression profile in patients with malaria." (PMID 29425228, 2018). "falciparum patients and 37 healthy controls also found a decrease in apoliprotein A in patients compared to controls, but a higher concentration of apolipoprotein B in malaria patients." (PMID 24314058, 2013).
meningioma (4 papers, 2014 to 2023). A generally slow growing tumor attached to the dura mater. "Similarly, Apolipoprotein B (APOB), which is significantly altered in meningioma in our study, has been associated with cancers and brain tumors." (PMID 37770851, 2023). "APOB and A-I were differentially abundant in malignant grades of meningioma, posing as a potential biomarker for the disease." (PMID 32587372, 2020). "Interestingly, a combination of Transferrin (TF) and FN1 along with TF and APOB showed better segregation as serum markers for meningioma grades." (PMID 37770851, 2023). "The proteins vimentin, alpha-2-macroglobulin, apolipoprotein B and A-I, and antithrombin III presented differential abundancy according to the degree of meningioma and may function as predictive markers that complement the histological diagnosis." (PMID 32587372, 2020). "Identified proteins like vimentin, alpha-2-macroglobulin, apolipoprotein B and A-I and antithrombin-III, which exhibited a sequential increase in different malignancy grades of meningiomas, could serve as potential predictive markers." (PMID 25413266, 2014).
multiple myeloma (4 papers, 2020 to 2025). "Apolipoprotein B mRNA-editing enzyme catalytic polypeptide-like (APOBEC) DNA cytosine deaminase 3B (A3B) is a DNA editing enzyme which induces genomic DNA mutations in multiple myeloma and in various other cancers." (PMID 31914134, 2020). "Innovative research has revealed mutational genomic aberrations caused by Apolipoprotein B mRNA-editing catalytic polypeptide-like (APOBEC) deaminases, as being critical for myeloma initiation and progression, and that genomic instability is involved in the pathogenesis of myeloma." (PMID 40973877, 2025).
nephrotic syndrome (4 papers, 2019 to 2023). A collection of symptoms that include severe edema, proteinuria, and hypoalbuminemia; it is indicative of renal dysfunction. "In the nephrotic syndrome, the elevated total cholesterol and triglyceride parallelly occur with the significant increase in apoA-I, apoA-IV, apoB, apoC, and apoE levels and the apoC-III to apoC-II ratio." (PMID 37061666, 2023). "Furthermore, Lp(a) is marked increased in nephrotic syndrome, mainly due to hypoalbuminemia through a process requiring apoB enhanced production, which determines an augmented synthesis of LDL particles to be combined into Lp(a)." (PMID 33916487, 2021).
osteonecrosis (4 papers, 2014 to 2025). A none disease characterized by death of bone tissue due to a lack of blood supply. "To further clarify the association of ApoAI and ApoB genetic polymorphism and osteonecrosis, we designed a larger sample-size case-control study." (PMID 25248404, 2014). "Similarly, the mutations in APOB (rs693 and rs1042031) increased the risk of steroid-induced osteonecrosis of the femoral head." (PMID 35405941, 2022). "The authors found C7623T polymorphism of ApoB gene was associated with osteonecrosis." (PMID 25248404, 2014). "Polymerase chain reaction was used to amplify the DNA fragments in promoter -75 G > A of ApoAI gene and EcoR I, Xba I and 3′-VNTR of ApoB gene in osteonecrosis patients and healthy controls." (PMID 25248404, 2014). "For the EcoR I, Xba I and 3′-VNTR of apoB gene, E + E+, X-X- and SS genotypes were more common in both osteonecrosis group and control group." (PMID 25248404, 2014). "However, in the present study, we did not found association of these SNPs in ApoB gene and osteonecrosis." (PMID 25248404, 2014).
pancreatic cancer (4 papers, 2015 to 2023). "We have found APOB downregulated in PDAC-S condition as compared to controls, suggesting its involvement also in pancreatic cancer development." (PMID 37628784, 2023). "While the relationship between APOB and pancreatic cancer has not been studied, the APOB mRNA editing catalytic subunit (APOBEC3C) was found to be the most expressed APOBEC enzyme in PDAC." (PMID 38067270, 2023).
pancreatitis (4 papers, 2023 to 2025). Inflammation of the pancreas. "These analyses collectively establish distinct causal mechanisms through which APOC3, APOB, and LPL contribute to pancreatitis risk." (PMID 41403918, 2025). "Factors such as age at onset,history of abdominal pain or pancreatitis, TG/TC ratio, and apoB levels werealso considered relevant for the clinical diagnosis of FCS." (PMID 41026863, 2025). "The drug‐target analyses suggest that targeting APOB, APOC3, and LPL are promising strategies to reduce the risk of multiple forms of pancreatitis, a finding that warrants further investigation." (PMID 41403918, 2025).
Parkinson disease (4 papers, 2013 to 2022). A progressive degenerative disorder of the central nervous system characterized by loss of dopamine producing neurons in the substantia nigra and the presence of Lewy bodies in the substantia nigra and locus coeruleus. "ApoB is associated with the future risk of Parkinson's disease (PD)." (PMID 36119695, 2022).
Sleep apnea (4 papers, 2024 to 2025). An intermittent cessation of airflow at the mouth and nose during sleep is known as sleep apnea. "Another participant presented elevated triglycerides, high ApoB, and an elevated WHR and only four children reported physical symptoms, including moderate exertional dyspnea, orthopedic issues affecting the hip or knee, and ongoing evaluation for suspected sleep apnea." (PMID 40487022, 2025).
adenoma (3 papers, 2019 to 2023). A neoplasm arising from the epithelium. "In adenoma-normal, downregulation of DEGs involved in metabolism of brush border proteins (LCT), lipids (APOB/A4), reactive oxygen species (GSTA2), and retinol (RBP2) was observed." (PMID 31211760, 2019). "Moreover, it was found that the glycated APOB form was more prevalent in CRC and adenoma tissues than non-cancerous tissues, suggesting a potential role for APOB in dysplastic and neoplastic development." (PMID 38067270, 2023).
age-related macular degeneration (3 papers, 2018 to 2024). Age-related loss of vision in the central portion of the retina (macula), secondary to retinal degeneration. "APOB is the major apolipoprotein in low-density lipoprotein cholesterol and has been identified in cholesterol-containing drusen and basal deposits of human eyes with age-related maculopathy." (PMID 29925537, 2018). "Background/Objectives: Research has suggested a potential relationship between apolipoproteins A (ApoA) and B (ApoB) and age-related macular degeneration (AMD)." (PMID 39767734, 2024).
amyotrophic lateral sclerosis (3 papers, 2020 to 2022). Amyotrophic lateral sclerosis (ALS) is a neurodegenerative disease characterized by progressive muscular paralysis reflecting degeneration of motor neurons in the primary motor cortex, corticospinal tracts, brainstem and spinal cord. "Total cholesterol, low-density lipoprotein cholesterol, high-density lipoprotein cholesterol, triglycerides, apolipoprotein AI, apolipoprotein B, and lipid ratios were measured at the time of amyotrophic lateral sclerosis diagnosis or shortly thereafter." (PMID 32221024, 2020). "By conducting a series of CSF filtration studies and global proteomic analysis of CSF, we identified apolipoprotein B-100 in sporadic amyotrophic lateral sclerosis CSF as the putative agent responsible for inducing motor disability, motor neuron degeneration and pathological translocation of TDP-43." (PMID 36043141, 2022).
Arrhythmia (3 papers, 2022 to 2025). Any cardiac rhythm other than the normal sinus rhythm. "We found that arrhythmias in aged flies may be associated with elevated apolipoprotein B. Inhibition of apoLpp mRNA, a homolog of apolipoprotein B, and early exercise training could reduce the occurrence of age-related arrhythmia risk and promote healthy aging." (PMID 36470666, 2022). "We investigated the effect of altered fat body apolipoprotein B gene expression on arrhythmias under aging conditions." (PMID 36470666, 2022). "Therefore, inhibiting the expression of apolipoprotein B may be an essential mechanism to reduce age-induced arrhythmias." (PMID 36470666, 2022).
arterial disease (3 papers, 2017 to 2025). "In the reverse MR analysis, only a causal relationship betweencoronary artery disease and ApoB was observed." (PMID 40475729, 2025).